PF4 (platelet factor 4)
Diseases named in the same sentence as PF4 in open-access papers (continued):
Sharing a sentence is not in itself a finding about the gene and the disease.
depression (9 papers, 2012 to 2025). "Lastly, comorbidities like depression and cardiac abnormalities can influence platelet activation, thus platelet reactivity, assessed by examining platelet factor 4 and or P‐selectin, should be examined in these patients when quantifying BDNF." (PMID 36722793, 2023). "The mRNA expression profile associated with Any Depression (AD) included four genes, three of them (PDGFA, PF4, and TGF-β1) were down-regulated (P-values: <0.0054, <0.0123 and <0.0152; respectively), while the STAT4 gene was up-regulated (P-value <0.0396)." (PMID 23139898, 2012). "In addition, for HCV patients with “Any Depression”, the PF4 gene was significantly down-regulated." (PMID 23139898, 2012). "Higher levels of PF4 and PPBP expression have also been observed in the blood of patients with depression." (PMID 38271077, 2024).
pulmonary hypertension (9 papers, 2016 to 2025). Increased pressure within the pulmonary circulation due to lung or heart disorder. "Thus, down-regulation of PF4 gene expression in our silica-induced model of pulmonary hypertension might promote angiogenesis and vascular remodeling in affected lungs." (PMID 27894297, 2016).
rheumatoid arthritis (9 papers, 2016 to 2025). A chronic, systemic autoimmune disorder characterized by inflammation in the synovial membranes and articular surfaces. "In this study, we evaluated the rates of seroconversion of anti-PF4/heparin Ab between patients with rheumatoid arthritis (RA) and with osteoarthritis (OA) who underwent total knee arthroplasty." (PMID 27558507, 2016).
colon carcinoma (8 papers, 2018 to 2024). "Statistically significant differences were found in the median levels of VEGF, PF4, and PDGF in platelets of patients with colon cancer compared with healthy individuals." (PMID 33219615, 2021). "Based on the earlier conducted functional enrichment analysis, we noticed that TIMP1, PF4 and SERPINA1 share a role in platelet degranulation, suggesting a key role for this biological process in colon cancer survival." (PMID 35008327, 2021). "Interestingly, Pf4 knockdown in HCT116 and HT29 colon cancer cells reduces clonogenic growth and cell proliferation." (PMID 38081853, 2023).
HIV-1 infection (8 papers, 2013 to 2020). The type species of lentivirus and the etiologic agent of acquired immunodeficiency syndrome (AIDS). "Plasma PF4 was found to be significantly elevated in both subacute and chronic HIV-1 infection indicating marked platelet activation." (PMID 33329587, 2020). "As its concentration increases, PF4 tends to form tetramers or higher-ordered forms, which enhance HIV-1 infection in vitro." (PMID 33050376, 2020). "During HIV-1 infections, activated platelets also produce PF4, which acts as an anti-viral cytokine." (PMID 33050376, 2020). "This (PF4) platelet-associated chemokine indeed blocks HIV-1 entry and neutralizes HIV-1 activity, that suggests a role for platelets in the defense against HIV-1 infection." (PMID 25913718, 2015). "On the contrary, platelets can also secrete CXCL4/PF4 that is supposed to inhibit HIV-1 infection of T cells; this exemplifies the complex relationship and interactions of platelets and viruses (for instance HIV1)." (PMID 25913718, 2015). "Previous studies have identified CXCL4 (also called platelet factor 4, or PF-4), derived from α-granules of activated degranulated platelets, as a “broad-spectrum” inhibitor of HIV-1 infection of T cells." (PMID 24282562, 2013). "Together these observations support the hypothesis that parallel elevations in both TGF-β1 and PF4 are elicited as a consequence of in vivo platelet activation during HIV-1 infection." (PMID 33329587, 2020). "For example, the common kinocidins, platelet factor 4 (PF-4) which is a small cytokine belonging to the CXC family, CXCL4, are inhibitor of HIV-1 and suppresses HIV-1 infection of T-lymphocytes." (PMID 30026673, 2018).
Hypertension (8 papers, 2017 to 2025). The presence of chronic increased pressure in the systemic arterial system. "Given the covariate influence of age, gender, BMI, hypertension, DM, hyperlipidemia, hemoglobin and uric acid, there was a significant positive correlation between PF4 and CAD." (PMID 28947991, 2017). "Interestingly, a previous study revealed that the plasma PF4 level was higher in hypertensive patients than in normotensive controls and increased with the stage of hypertension." (PMID 38137539, 2023).
Lipedema (8 papers, 2022 to 2025). Disorder of adipose tissue characterized by symmetric and bilateral enlargement of the lower extremities due to abnormal deposition of subcutaneous fat often in obese women. "The identification of diagnostic markers for lipedema remains a challenge, but platelet factor 4 in plasma-derived exosomes is elevated in lipedema and has high sensitivity and specificity to discriminate patients with lipedema from controls." (PMID 40149538, 2025). "In the context of lipedema, elevated M2 macrophages, lymphocyte subtypes, and PF4—an inflammatory marker—have been associated with the condition, indicating a potential link between inflammation and the pathogenesis of lipedema." (PMID 39590304, 2024). "Taken together, these findings suggest an association between lipedema and lymphatic abnormalities, and exosomal platelet factor 4 may become a biomarker for the diagnosis of this disease." (PMID 40149538, 2025). "Elevated levels of platelet factor 4 (PF4/CXCL4) were reported in circulating blood plasma exosomes of patients with lipedema." (PMID 40425048, 2025). "A mass spectrometry analysis identified elevated levels of platelet factor 4 in exosomes isolated from the plasma of patients diagnosed with lipedema (n = 15; stage 1 (n = 4), stage 2 (n = 6), stage 3 (n = 5); BMI 36 ± 9 kg/m2) compared to the controls." (PMID 40149538, 2025). "Quantification of platelet factor 4 levels in plasma exosomes in 15 patients with lipedema and 12 healthy controls resulted in an AUC of 0.95, with a sensitivity and specificity of 0.87 and 0.91, respectively, for a cut-off of 9.71." (PMID 36310013, 2022). "Recent evidence of elevated platelet factor 4 (PF4) in patients with lipedema, a circulatory marker shared in patients with lymphedema, further supports the lymphatic dysfunction-adipose expansion hypothesis." (PMID 35743063, 2022).
ovarian carcinoma (8 papers, 2013 to 2025). A malignant neoplasm originating from the surface ovarian epithelium. "Upon validation with complementary IHC staining for FFPE HGSOC tissue specimens, we identified six protein biomarkers to predict the prognosis of HGSOC; expression levels of AAT, NFKB, PMVK, VAP1, FABP4, and PF4 in ovarian cancer tissue were associated with PFS." (PMID 32224886, 2020). "Compared to plasma from healthy controls, plasma from patients with untreated ovarian cancer had elevated P-selectin (p = 0.03) and beta-TG (p = 0.02) levels, while PF4 levels were the same (p = 0.96)." (PMID 39518024, 2024). "Patients with ovarian cancer undergoing chemotherapy had significantly reduced plasma P-selectin and PF4 in comparison to untreated and healthy patients and significantly reduced plasma beta-TG in comparison to patients with ovarian cancer." (PMID 39518024, 2024). "Our observation of elevated beta-TG levels in patients with untreated ovarian cancer and no change in PF4 levels is consistent with previous reports in patients with lung and breast cancers." (PMID 39518024, 2024).
glioblastoma (7 papers, 2010 to 2023). The most malignant astrocytic tumor (WHO grade IV). "We found an association between ILK1 levels and AKT phosphorylation at Ser473, which indicates that PF4-DLR treatment for 10 days reduces glioblastomas growth by inhibiting the AKT pathway." (PMID 21060779, 2010). "The activity of PF4-DLR can be increased by simultaneously treating mice orthotopically implanted with glioblastomas, with ILK1-specific siRNA." (PMID 21060779, 2010). "In conclusion, we found that ILK1 is involved in tumor response to anti-angiogenic therapy with PF4-DLR in a xenografted model of glioblastoma." (PMID 21060779, 2010). "As part of validation of the proteomic analysis, the expression of some of the identified proteins was tested by immunoblotting using protein extracts from glioblastomas treated with PF4-DLR for 10 and 20 days." (PMID 21060779, 2010). "As most of these proteins seem to be functionally involved in positively regulating tumor growth, glioblastomas may develop resistance to PF4-DLR by regulating this specific set of proteins." (PMID 21060779, 2010). "After 20 days of treatment, glioblastomas are still responsive to PF4-DLR." (PMID 21060779, 2010).
Thromboembolism (7 papers, 2013 to 2024). The formation of a blood clot inside a blood vessel that subsequently travels through the blood stream from the site where it formed to another location in the body, generally leading to vascular occlusion at the distant site. "PF4 is a platelet-activating chemokine that induces thrombocytosis and thromboembolism." (PMID 32224886, 2020). "This leads to megakaryocyte activation, biogenesis of activated platelets, and release of thromboxane A2 (TxA2) and PF4 that further activates platelets and their traversal through the cerebral vein sinuses, leading to thromboinflammation, CVST, and thromboembolism in other blood vessels." (PMID 37896978, 2023).
venous thromboembolism (7 papers, 2014 to 2025). Occlusion of the lumen of a vein by a thrombus that has migrated from a distal site via the blood stream. "High serum PF4 levels were associated with poor survival and an increased risk of venous thromboembolism in patients with pancreatic adenocarcinoma." (PMID 32224886, 2020). "However, it was found to be unsafe due to the increased risk of venous thromboembolism related to induced antibodies to platelet factor 4 (Anti-PF4)." (PMID 34696205, 2021).
endometriosis (6 papers, 2012 to 2025). The growth of functional endometrial tissue in anatomic sites outside the uterine body. "Notably, Platelet Factor 4 (PF4), also known as chemokine (C-X-C motif) ligand 4 (CXCL4), exhibits high expression on macrophages in endometriosis but low expression on TAMs in clear cell ovarian cancer." (PMID 41445742, 2025).
glioma (6 papers, 2010 to 2025). A benign or malignant brain and spinal cord tumor that arises from glial cells (astrocytes, oligodendrocytes, ependymal cells). "The viral-vector-mediated transfection of the PF4 gene suppressed endothelial cell proliferation and angiogenesis in a mouse xenograft model with glioma, and this was associated with the prolonged survival of the tumor-bearing mice." (PMID 21693026, 2011). "In a focused examination of the predominant biological pathway in glioma, specifically the proliferation pathway, it was observed that the PF4, PF8, PF15, and PF35 features exhibit a positive correlation with the activity of these pathways." (PMID 39845415, 2025). "In our lab, PLGA has been used to produce particles loaded with PEX, a fragment of matrix metalloproteinase (MMP)-2, or platelet factor 4 fragments (PF-4/CTF) for the delivery of these angiogenesis inhibitors to glioma bearing nude mice." (PMID 20932320, 2010). "We then tested whether the inhibitory activity of PF4-DLR can be increased in vivo by combined treatment with PF4-DLR and ILK1 siRNA in the experimental glioma model in mice." (PMID 21060779, 2010). "Benny and colleagues demonstrated the delivery of two endogenous anti-angiogenic inhibitors, hemopexin (PEX) and a fragment of platelet factor 4 (PF-4) (PF-4/CTF), in vitro and in vivo for human glioma therapy using PLGA microspheres, with glioma growth inhibition observed." (PMID 20414333, 2010).
heart failure (6 papers, 2015 to 2025). Inability of the heart to pump blood at an adequate rate to meet tissue metabolic requirements. "Authors have reported significantly higher levels of plasma haemostatic markers such as D-dimer, fibrinogen, platelet factor 4 in cases of heart failure." (PMID 35901057, 2022). "Furthermore, we observed pro-arrhythmic genes associated with heart failure and thrombosis after MI in URI predominantly Kcne3 and Pf4." (PMID 36012110, 2022). "Patients with heart failure show decreased gastrointestinal absorption of antiplatelet drugs, elevated markers of platelet activation including thromboglobulin, Platelet Factor 4, P-Selectin and platelet-derived adhesion molecules and increased platelet volume." (PMID 25799149, 2015).
interstitial lung disease (6 papers, 2016 to 2025). A diverse group of lung diseases that affect the lung parenchyma. "Some studies have reported increased PF4 concentrations in bronchoalveolar lavage fluid (BALF) from individuals with scleroderma interstitial lung disease." (PMID 40483519, 2025). "PF4 levels are elevated in the BALF of patients with scleroderma interstitial lung disease, and platelet activation occurs in the lungs." (PMID 37118713, 2023).
myelofibrosis (6 papers, 2022 to 2025). A partial or complete replacement of the bone marrow stroma by fibrous tissue. "Dnm2fl/fl Pf4-Cre (Dnm2Plt–/–) mice lacking the endocytic GTPase dynamin 2 (DNM2) in platelets and megakaryocytes (MKs) develop hallmarks of myelofibrosis." (PMID 36110936, 2022).
Obesity (6 papers, 2012 to 2025). Accumulation of substantial excess body fat. "In monocytes, we identified that expression of five genes was significantly upregulated by HFD-induced obesity, including Ccl6, Fn1, Lpl, Pf4 and Retnla." (PMID 32785175, 2020). "Obesity was also associated with increased expressions of angiogenesis-related proteins, in particular, angiogenin, endoglin, endostatin, endothelin-1, IGFBP-3, leptin, MMP-3, PAI-1, TIMP-4, CXCL16, platelet factor 4, DPPIV and coagulation factor III." (PMID 22748184, 2012). "Although PF4 may not have a direct reported association with MUO, platelet activation and PF4 secretion are present in obesity." (PMID 40376303, 2025). "For example, bioinformatic comparison of transcriptomes in polycystic ovary syndrome (PCOS), obesity, and T2DM identified jointly dysregulated genes (including IGF2R, the insulin-like growth factor 2 receptor) and network “hub” proteins such as STAT3, IL1B, and PF4." (PMID 41303351, 2025). "At the family level, Lachnospiraceae, Erysipelotrichaceae, and Bacteroidaceae, which were enriched in the obesity-related groups, either with or without Pso, displayed positive correlations with all the investigated proinflammatory cytokines and chemokines, except IL-10 and PF4." (PMID 40869018, 2025).
scleroderma (6 papers, 2015 to 2025). Scleroderma is a rare autoimmune connective tissue disorder characterized by abnormal hardening of the skin and, sometimes, other organs. "We discovered an unexpected signaling pathway for chemokine (C-X-C motif) ligand 4 (CXCL4)/platelet factor 4 (PF4) and its role in the pathogenesis of scleroderma." (PMID 32849553, 2020).
Thrombocytosis (6 papers, 2017 to 2025). Increased numbers of platelets in the peripheral blood. "FcRγIIA-mediated signaling of PF4-anti-PF4 IgG complexes induces pro-coagulant thrombocytosis, platelet/neutrophil aggregation, and NETosis." (PMID 40733710, 2025). "Thrombocytosis can also lead to HR as platelet factor 4 (PF4) released from activated platelets binds to UFH, therefore reducing the bioavailability of heparin." (PMID 39303137, 2024). "Heparin can also induce thrombocytosis by potentiating megakaryopoiesis—in particular, by inhibiting platelet factor 4 (PF4)." (PMID 36232759, 2022). "Importantly, thrombocytosis in PV and ET is reflective of excessive platelet production and turnover, and platelets in MPN are known to circulate in an activated state, thus providing ample PF4 which could promote the formation of anti-PF4/heparin antibodies in PV and ET." (PMID 28698883, 2017).
cerebral malaria (5 papers, 2010 to 2024). A sequestration of Plasmodium falciparum in the brain, which can cause coma and/or seizures. "PF4/CXCL4 has been shown to contribute with leukocyte trafficking into the injured cerebral vasculature during experimental cerebral malaria in mice." (PMID 34991449, 2022). "We have demonstrated using the Plasmodium berghei ANKA mouse model of experimental cerebral malaria (ECM) that platelets are activated by direct CD36 dependent interactions with Plasmodium iRBCs leading to increased circulating levels of platelet factor 4 (PF4/CXCL4)." (PMID 20454664, 2010).
Cognitive impairment (5 papers, 2023 to 2025). Abnormal cognition is characterized by deficits in thinking, reasoning, or remembering. "This study reported that exposure improved cognitive impairments associated with hippocampal function, as well as implicated platelet factor 4 (PF4) in the observed benefits." (PMID 39154047, 2024). "Although the off-target binding of an anti-Aβ monoclonal antibody to PF4 causes acute and chronic toxicity in cynomolgus monkeys, the manner in which PF4 dominantly modulates Aβ deposition and subsequently attenuates cognitive impairment deserves further clinical investigation." (PMID 40193115, 2025). "We also demonstrate that increasing the systemic levels of the platelet-derived exerkine CXCL4/platelet factor 4 (PF4) ameliorates age-related regenerative and cognitive impairments in a hippocampal neurogenesis-dependent manner." (PMID 37587147, 2023). "In old mice, PF4 decreased cognitive deficits and restored aging-induced increases of select factors associated with cognitive performance in the hippocampus." (PMID 37587231, 2023). "Accordingly, these findings support the proposal that PF4, as a critical anti-aging component, could modulate age-related cognitive impairment in aged mice or AD patients." (PMID 40193115, 2025). "Overall, recent studies have demonstrated that increasing systemic levels of PF4 in the cerebrovasculature could ameliorate age-related neurodegeneration and cognitive impairment in a hippocampal neurogenesis-dependent manner." (PMID 40193115, 2025). "For example, a recent study reported that proanthocyanidins, as a dietary supplement, could substantially improve systemic inflammation, raise levels of the anti-inflammatory cytokine PF4, and significantly lower pro-inflammatory factors in the blood to rescue cognitive impairment in aging mice." (PMID 40193115, 2025). "However, it is unclear whether serum PF4 levels could be detected early in the preclinical stage of the AD spectrum population, especially in patients with subjective cognitive impairment and mild cognitive impairment." (PMID 40193115, 2025).
cystic fibrosis (5 papers, 2018 to 2025). Autosomal recessive disorder caused by pathogenic variants in the CFTR gene (cystic fibrosis transmembrane conductance regulator), which encodes a chloride and bicarbonate channel expressed in epithelial cells, and follow the diagnosis criteria. "Since P. aeruginosa may cause chronic lung infections in cystic fibrosis patients, we next tested whether Pf4 transfer could occur in the artificial sputum medium (ASM), which is a viscous liquid environment promoting biofilm formation." (PMID 38365255, 2024). "People with Cystic Fibrosis (pwCF) experience chronic airway infection with Pa and a significant proportion have high numbers of Pf4 in their airway secretions." (PMID 38275975, 2024). "Future avenues of investigation include determining whether Pf4 phages isolated from sputum form individuals with cystic fibrosis contain OMVs and whether a correlation exists between patients with the highest OMV sputum content and worst infection control outcome." (PMID 37965262, 2023).